PPARG (peroxisome proliferator activated receptor gamma)
Diseases named in the same sentence as PPARG in open-access papers (continued):
Sharing a sentence is not in itself a finding about the gene and the disease.
infection (175 papers, 2006 to 2026). The state of being infected such as from the introduction of a foreign agent such as serum, vaccine, antigenic substance or organism. "Infection with Hp did not modulate the levels of mRNA for UCP1, IL33 or PPARγ in EWAT of HFD-treated animals at 5 weeks post infection suggesting a minor role of these factors in Hp-associated weight control." (PMID 35499991, 2022). "Together the diversity of these regulations and their apparently contradictory consequences on PPARγ activity underscore the wide spectrum of cell signaling alterations caused by the infection." (PMID 34445581, 2021). "In cultured PKR1-overexpressing tcf21+ CPFs caused by Adv-PKR1 infection, the expression of PPARγ and CEB/Pα was decreased, whereas Flk-1 and calponin expression was increased, indicating the cell-autonomous regulation of tcf21+CF cell fate by PKR1." (PMID 29038558, 2017). "Last, Oil red O staining showed that infection was associated with the accumulation of lipid droplets in the cytoplasm of host NSCs, indicative of enhanced lipid metabolism and thus of PPARγ activity." (PMID 27078877, 2016). "Regarding that PGZ effects are PPARγ-mediated, a Western blotting analysis was conducted for this host cell-encoded protein following ECwt infection of villi in an in vitro system." (PMID 27382365, 2016). "In contrast, we observed that infection of cytotrophoblasts with MAFP-treated HCMV particles abolished PPARγ activation associated with infection." (PMID 26171612, 2015). "In this clinical trial adjunctive therapy with PPARγ agonists was associated with significantly faster parasite clearance time and reduced systemic inflammatory responses to infection." (PMID 24603727, 2014). "During the early stage of infection, PPARγ deficiency significantly upregulated IL-6 and TNF-α expression in malnourished mice." (PMID 23469071, 2013). "Simulation results showed a marked impact of the loss of PPARγ on myeloid cell populations following infection." (PMID 24039925, 2013). "More importantly, PPARγ deficient mice were able to generate a Th17 effector response by day 14 post-infection." (PMID 23469071, 2013). "When cells were exposed to the replication competent NL4.3BaL 24 h post-nucleofection, PPARγ silencing was associated with a significant increase in HIV-DNA integration in 5/5 subjects at day 3 post-infection (range increase: 150-200%)." (PMID 24359430, 2013). "Under these experimental conditions, we also observed reduced numbers of bacteria in the liver and spleen, which indicates that the improved function of PPARγ-deficient macrophages alone is already sufficient to control infection." (PMID 22629382, 2012). "The expression of PPARγ has been shown to be augmented in macrophages after infection with pathogenic bacteria such as Mycobacterium tuberculosis and Salmonella enteridis." (PMID 22629382, 2012). "This may explain how PPARγ can cause immunosuppression to the extent of increasing risk of infection." (PMID 35003101, 2021). "However, considering the previously stated increase in risk of infection, a dual PPARα/γ agonist would be a safer approach, especially considering both PPARγ and PPARα inhibit iNOS related ROS production." (PMID 35003101, 2021). "Myeloid cell-specific loss of PPARγ has been reported to enhance chemokine and adhesion molecule expression leading to improve recruitment of inflammatory Ly6Chi monocytes to sites of inflammation and infection." (PMID 24039925, 2013). "Moreover, myeloid cell-specific loss of PPARγ enhanced chemokine and adhesion molecule expression leading to improved recruitment of inflammatory Ly6Chi monocytes to sites of infection." (PMID 22629382, 2012). "By preventing HIV-1 replication, in addition to DC migration, pro-inflammatory cytokine and chemokine production, and trans-infection, PPARγ and LXR ligands may block the dissemination of DC-associated virus from the local site of infection to regional lymph nodes." (PMID 20617179, 2010).
infection (continued). "To investigate further, we established a stable BV2 microglial cell line overexpressing PPARγ using lentiviral infection." (PMID 41355958, 2026). "At 48 hr post-infection, the transcript levels of Peroxisome proliferator-activated receptor-gamma (PPARG) were upregulated by 5–6-fold." (PMID 41358489, 2025). "Co-transfection and co-infection experiments showed that both YTHDC1 and its W378A mutant, but not the YTHDC1 ∆IDR variant, were able to prevent ARIH2-induced degradation of PPARγ in HEK293T cells, primary brown adipocytes, and primary white adipocytes." (PMID 40355558, 2025). "(B) Kinetic increase in the gene expression of Pparγ transcript levels across different weeks post-infection (C) Immunoblot showing increased PPARγ protein levels in primary hepatocytes (PHCs) (MOI: 10) at 5-, 24-, and 48 hr post-infection." (PMID 41358489, 2025). "To validate, we performed quantitative real-time PCR analysis of the PPARG gene in the infected HepG2 at 48 hr post-infection." (PMID 41358489, 2025). "Infection of the hepatocytes in the in vivo aerosol mice model can be consistently observed post-week, 4 along with enhanced expression of PPARγ and drug-metabolizing enzymes." (PMID 41358489, 2025). "Immunoblot also revealed a greater level of PPARγ protein in primary mouse hepatocytes at 24 hr and 48 hr post-infection in the Mtb-infected cells." (PMID 41358489, 2025). "The evaluation of the transcriptional expression of PPARγ evidenced that at both 1 and 21 days of differentiation after infection, PPARγ was upregulated by SARS-CoV-2 BA." (PMID 40006897, 2025). "Previous literature suggests that FLUAV infection of AMs not only induces death by apoptosis, but also impairs the immune activity of AMs via peroxisome proliferator-activated receptor gamma (PPARγ) repression." (PMID 38377132, 2024). "For example, the DEHP metabolite MEHP has been shown to inhibit and induce apoptosis of immune cells (i.e., B cells, which produce antibodies to protect from infection) in bone marrow, which is thought to occur through activation of PPARγ." (PMID 38390895, 2024). "Here, we showed that infection with a virus that is highly adapted to pigs (sOH/04) resulted in downregulation of PPARγ." (PMID 38377132, 2024). "As a result, PPARγ has been demonstrated to have a protective function against infections by modulating the immune response and lowering inflammation." (PMID 36831317, 2023). "Infection with Usp7-overexpressing adenovirus markedly elevated PPARγ levels in hepatocytes and increased Usp7 expression." (PMID 36834633, 2023). "In this regard, up-regulation of PPARγ expression on Mf after infection by Mycobacterium bovis (BCG), Mtb, Listeria monocytogenes, and Mycobacterium leprae has been reported." (PMID 37187471, 2023). "Cadmium and infection increased ERK activation to regulate PPARγ degradation in monocyte-derived macrophages." (PMID 36928191, 2023). "Our previous observations with siRNA silencing of PPARγ showed a decrease in M. tb-induced MCL-1 gene expression beginning at 6h post-infection." (PMID 37000865, 2023). "Conversely, expression of the pro-inflammatory IL18 in the jejunum was significantly decreased by infection (fold change − 1.2), and so were type-2 associated gene CCL22 (fold change − 2.1) and adipocyte regulator PPARG (fold change − 1.3)." (PMID 38081984, 2023). "The effects of PPAR activation on MHV68 replication were examined by treating BMDMs with agonists for PPARα (fenofibrate or WY14643), PPARβ/δ (GW501516), or PPARγ (rosiglitazone) prior to infection." (PMID 36715509, 2023). "We next examined the effect of H37Ra infection on PPARγ expression in THP-1 macrophage-derived foam cells." (PMID 35432274, 2022). "In the context of a viral productive cycle, HAdV-D36 modulated the expression of the adipogenic genes, C/EBPα, C/EBPβ and PPARγ, as well as intracellular lipid accumulation, and the infection was accompanied by altered expression of glucolytic genes." (PMID 36237435, 2022).
infection (continued). "ART-treated infection impacted the metabolic fraction (with elevated expression of PPARγ and CEBPα), the extracellular matrix (with elevated expression of COL1A2 and HIF-1α), and the inflammatory profile." (PMID 36231066, 2022). "Both corticosteroids and PPARγ agonists have been shown to impact the phenotype of macrophages during infection." (PMID 35575507, 2022). "Treatment with pioglitazone (PGZ), a PPARγ ligand, increased survival from PR8 infection, decreased M1 macrophage gene expression, and increased PPARγ mRNA in lungs." (PMID 36052067, 2022). "Compared with the uninfected control group (0 h), the expression of PPARγ gradually decreased with prolonged infection time, which demonstrated that H37Ra infection induced a time-dependent decrease in PPAR expression in macrophages." (PMID 35432274, 2022). "In this study, we confirmed that H37Ra infection decreased PPARγ expression in a time-dependent manner in THP-1 macrophage." (PMID 35432274, 2022). "To investigate the role of PPARγ in lipid accumulation within Mtb H37Ra-infected macrophages, we pretreated macrophages with a PPARγ agonist BRL49653 or antagonist GW9662 followed by H37Ra infection." (PMID 35432274, 2022). "In conclusion, our findings demonstrate that H37Ra infection reduces PPARγ expression and induces FM formation in a time-dependent manner in THP-1-derived foamy macrophages." (PMID 35432274, 2022). "By contrast, pre-treatment with Pioglitazone (PPARγ agonist) inhibited bacterial clearance; notably, the bacterial burden was significantly higher at both 3 and 6 h after infection." (PMID 35288651, 2022). "In previous studies, we found that EPO promoted infection resolution and ameliorated inflammatory response through a ligand-activated transcriptional factor peroxisome proliferator–activated receptor gamma (PPAR-γ) in macrophages." (PMID 36016936, 2022). "PPARγ can certainly be seen as a therapeutic target for infection and immune related diseases but should be done so with the consideration of its indication of poor prognosis through inhibition of bacterial clearance." (PMID 35003101, 2021). "9-HODE was also found to dramatically increase PPARγ levels and activity in uninfected NSCs, recapitulating the effect of infection." (PMID 34445581, 2021). "Our data show that hypoxia-inducible factor-1 (Hif-1a) is significantly increased, whereas peroxisome proliferator activated receptor gamma (Pparg) is significantly decreased, following infection with the organism." (PMID 34066663, 2021). "In the infected adult brain, the role of PPARγ in the host response to infection appeared beneficial against inflammation, oxidative stress and viral replication, as exemplified in HIV infection." (PMID 34445581, 2021). "This study evaluated changes in Nrf2 expression and its downstream targets heme oxygenase (HO-1) and peroxisome proliferator-activated receptor gamma (PPARγ) in fetal membranes during OS and infection in vitro." (PMID 32858866, 2020). "15-keto-prostaglandin E2 activates host peroxisome proliferator-activated receptor gamma (PPAR-γ) to promote Cryptococcus neoformans growth during infection." (PMID 35582457, 2020). "IPA indicated that expression of this set of genes is likely to be controlled by PPARG at 8 h post-infection." (PMID 32793510, 2020). "Few results support the LPA role during infection or inflammation, and more studies deserve to be done considering its role in human macrophage formation with PPARγ as the key master regulator." (PMID 31878214, 2019). "This indicated that PPARG also has significant role in the regulation of ROS and NO production during infection process." (PMID 31258517, 2019). "Infection of Schwann cells with M. leprae also supported the importance of PPARG in mycobacterial replication and survival." (PMID 31258517, 2019).
infection (continued). "After precipitation with anti-PPARγ antibody, the quantitative analysis showed that compared with the 0-h non-infection group, the amount of precipitated Acc, Adipoq and Lpin1 after 48 h of Ad36 induction increased by 8.99, 7.86, and 2.10 folds, respectively." (PMID 30902099, 2019). "Here, we investigated the functional cooperation between FABP5 and PPARγ in a monocytic-derived cell line and in human PBMCs in response to CS exposure and infection." (PMID 30877402, 2019). "Compared with the 0-h non-infection group, the amount of the precipitated PPARγ decreased by 3.27 times after 24 h of induction with Ad36, and the immunoprecipitation amount decreased by 4.7 times after 48 h of induction." (PMID 30902099, 2019). "Vitamin D treatment of Mtb-infected macrophages downregulated PPARγ activation, abating the infection-induced LD accumulation and ultimately reducing bacterial growth." (PMID 30991653, 2019). "Western blot analysis confirmed these findings, since iNOS expression increased upon infection, decreased after treatment with PPARγ agonist and this decline was reversed in silenced cells." (PMID 31993046, 2019). "Increased expression and nuclear localization of PPARG was observed upon infection with M. bovis BCG strain." (PMID 31258517, 2019). "Overall, PPARγ down-regulates pro-inflammatory immune responses during infection, which is vital during the resolution phase to prevent inflammation-induced host damage." (PMID 30897154, 2019). "As previously reported by our group, infection of mice with T. cruzi increases PPARγ expression in the heart and in peritoneal macrophages." (PMID 29312293, 2017). "Infection of cells with RV is significantly inhibited when cells are treated with peroxisome proliferator-activated receptor gamma (PPARγ) and NSAIDs, indicating that RV has pro-inflammatory actions." (PMID 28261111, 2017). "Meanwhile, the immunofluorescence analysis showed that ECwt infection increased the percentage of villus cells being positive to both cytoplasmic and nuclear PPARγ, whereas PGZ treatment appears to counteract this enhancing effect." (PMID 27382365, 2016). "Recent advances in our understanding of PPARγ's role in immunity, infection, and inflammation offer the opportunity for intervention with a novel approach to bacterial infections." (PMID 27774097, 2016). "ECwt infection of mice increased PPARγ expression by 110.35 ± 10.5%, 46.02 ± 6.78%, 23.00 ± 4.80%, and 29.07 ± 5.39% in villus cells at 12, 24, 36, and 48 h.p.i., respectively, relative to uninfected control mice." (PMID 27382365, 2016). "The ELISA results showed that ECwt infection significantly led to an increased expression of PPARγ, NF-κB, COX-2, and Hsc70 at 12 h.p.i." (PMID 27382365, 2016). "In particular, we investigated the outcome of infection on Peroxisome Proliferator-Activated Receptor gamma (PPARγ, a key protein in the regulation of metabolism, inflammation and cell differentiation." (PMID 27078877, 2016). "Taking into account that the in vivo infection system analyzed is an asynchronous one, the subcellular localization percentages obtained for PPARγ and NF-κB are reflecting an average state of the infection process rather than a synchronous viral cycle." (PMID 27382365, 2016). "Our findings thus show that infected NSCs release soluble mediators able to activate PPARγ expression in uninfected NSCs, similar to direct infection per se, and that lipid components contribute to this bystander effect." (PMID 27078877, 2016). "Next, we investigated which PPARγ activator lipids are released upon infection by HCMV using a model closer to the physiological context." (PMID 26171612, 2015). "13-HODE treatment of uninfected HIPEC recapitulated the effect of infection (PPARγ activation, migration impairment)." (PMID 26171612, 2015). "This prompted us to search for PPARγ activating lipids generated in HIPEC at early stages of infection." (PMID 26171612, 2015).
infection (continued). "Infection of cytotrophoblasts with MAFP-treated HCMV particles decreased PPARγ-dependent inhibition of cell migration in a manner similar to that caused by UV irradiation of the inoculum, or by treatment of HIPEC with the PPARγ synthetic inhibitor, GW9662." (PMID 26171612, 2015). "Collectively, our results imply that these inflammatory signaling circuits are orchestrated by S. Typhimurium during the early phases of infection via the regulation of epithelial PPARγ, which is pivotal for the entire process." (PMID 24465207, 2014). "Immunoblotting revealed a similar down-regulation of PPARγ expression at the protein level in the colon 24 h after infection." (PMID 24465207, 2014). "In contrast, treatment of B. abortus-infected mice with PPARγ agonist led to increased expression of M2 markers in splenic macrophages and enhanced bacterial count in the spleen during the chronic infection phase." (PMID 25505468, 2014). "Treating Brucella abortus-infected mice with a PPARγ inhibitor led to a significant decrease in splenic colonization during the chronic phase of infection." (PMID 25505468, 2014). "After 3 days of infection, PPARγ-MEFs began to accumulate LDs, and the number of LDs stained by Oil Red O increased for the subsequent 3 days." (PMID 23734208, 2013). "In the GLN, the differences between the T cell specific PPARγ knockout and the wild-type were significantly noticeable during the whole period of infection." (PMID 24039925, 2013). "Specifically, we used the compound 2-chloro-5-nitrobenzanilide (GW9662), a potent PPARγ antagonist, and conditional PPARγ knockout mice to delineate the impact of PPARγ during infection with EAEC in nourished and malnourished mice." (PMID 23469071, 2013). "Our results showed a statistically significant expansion of Th1 in the T cell-specific PPARγ null system when compared to the wild-type starting around day 35 and increasing the difference throughout the infection up to day 60 in the gastric LP." (PMID 24039925, 2013). "First, our deterministic ODE model shed some new light on CD4+ T cell distribution after infection as well as the role of PPARγ during infection." (PMID 24039925, 2013). "PPARγ also acts on infected cells and limits replication and subsequent infection spreading to neighboring cells by acting at post-integration levels, likely during transcription." (PMID 24359430, 2013). "In the case of the GLN, the myeloid cell-specific PPARγ knockout model showed significant differences when compared to the wild type up to day 30 post-infection." (PMID 24039925, 2013). "PPARγ activation was demonstrated during infection by BCG and M. tuberculosis, as well as its major cell-wall immune-regulatory lipoglycan, namely, ManLAM that culminates with an anti-inflammatory response and downregulation of macrophage functions." (PMID 22851964, 2012). "Flow cytometric analyses of immune cell populations indicates an increased percentages of IL-17+ and RORγt+ CD4+ T cells following the infection as well as increased percentages of Th17 cells in spleens of T cell-specific PPARγ null mice." (PMID 23071818, 2012). "Most patients had more than one pathogen detected in BALF, so we were unable to meaningfully analyze the effects on PPARγ gene expression of infection with each individual type of microbe because of possible interactions between them." (PMID 22860094, 2012). "We observed a rapid and pronounced increase in the expression of PPARγ within 30 minutes after infection, as shown by immunoblot and immunofluorescence analysis of infected human monocytes." (PMID 22629382, 2012). "Then, at 4 weeks after infection, the livers and spleens were harvested and quantified for PPARγ, iNOS, cytokines, and parasite load." (PMID 22448168, 2012). "Here, we have investigated the role of the potent anti-inflammatory transcription factor PPARγ in regulating the early innate immune response of myeloid cells against infection with L. monocytogenes." (PMID 22629382, 2012).